MTOR (mechanistic target of rapamycin kinase)
Diseases named in the same sentence as MTOR in open-access papers (continued):
Sharing a sentence is not in itself a finding about the gene and the disease.
cancer (continued). "This is because inhibition of PI3K/Akt-mTOR-HIF-1 decreases lactate and ATP concentrations as well as the expression of GLUT1, HK-2, and PFK-1 in cancer cells." (PMID 35682652, 2022). "TQ has been shown to inhibit many signaling pathways, including PI3K/Akt /mTOR and JAK/STAT signaling in several cancer cells." (PMID 36145344, 2022). "Although SHIP2 can suppress PI3K/Akt signaling and inhibits cancer progression, its role in regulating the PI3K/AKT/mTOR signaling pathway in HCC remains poorly understood." (PMID 36344496, 2022). "On the other hand, SRC, CASP3, EGFR, ERBB2, mTOR, MMP9, and HIF1A followed the proteoglycans in cancer (degree 7)." (PMID 35959427, 2022). "Our findings reveal a previously unrecognized mechanism in which NOP56 and mTOR cooperate to play a homeostatic role in the response to oxidative stress and suggest a new rationale for the treatment of KRAS-mutant cancers." (PMID 35039048, 2022). "mTOR, MAPK, and nuclear factor kappa B (NF-κB) are among the signaling pathways involved in cancer formation." (PMID 36428613, 2022). "PI3K/Akt/mTOR and MAPK signaling pathways had been demonstrated to be involve in cell proliferation, motility, survival and apoptosis of cancer cells." (PMID 36506551, 2022). "SSD and its active constituents exert their anti-cancer effects by networking with complex transcription factors, PI3K/Akt/mTOR." (PMID 36139460, 2022). "The anti-cancer properties of Kmp primarily occur via modulation of apoptosis, MAPK/ERK1/2, P13K/Akt/mTOR, vascular endothelial growth factor (VEGF) signalling pathways." (PMID 36557997, 2022). "Since mTOR plays an important role in tumor progression, AMPK-induced inactivation is a promising therapeutic strategy in cancer treatment." (PMID 36012522, 2022). "The pathways activated by HELLS, mainly in cancers, were apoptosis, cell cycle, DDR, EMT, and hormone AR, and those inhibited are hormone AR, RAS/MAPK, PI3K/AKT, RTK, and TSC/mTOR." (PMID 35774795, 2022). "Because of its importance in coordinating cell biosynthesis and aerobic glycolysis in cancer cells, the PI3K-Akt-mTOR signal transduction pathway is also considered a candidate target pathway in anticancer therapy." (PMID 36276846, 2022). "Cellular migration, proliferation and survival of cancer cells as well as endothelial cell differentiation are mainly driven by VEGF/VEGFR activation, which in turn activates the PI3K/Akt/mTOR signalling pathway." (PMID 36474188, 2022). "The results showed that the expression of MTOR in MGF group was lower than that in MT group, indicating that MGF can inhibit the growth of cancer by inhibiting the growth of cancer cells in cancer tissues." (PMID 36386222, 2022). "A recent study found that macropinocytosis reduces sensitivity to mTOR inhibition by restoring AKT phosphorylation at serine 473, and leading to cancer cell proliferation." (PMID 36046825, 2022). "mTOR is a key kinase downstream of PI3K/Akt, and it plays a role in regulating the growth, proliferation, survival, and even metastasis of cancer cells." (PMID 35321703, 2022). "What’s more, mTOR was considered as a mediator in TGF-β pathway that intensified stemness and drug resistance in cancer." (PMID 36601127, 2022). "In cancer cells, this pathway is highly activated, and the inhibition of the PI3K/AKT and mTOR pathways induces apoptosis and has anticancer effects in various cancers." (PMID 36142874, 2022).
cancer (continued). "The Cancer Proteome Atlas (TCPA) created a Kaplan Meier (KM) plot for miR-520c-3p targets AKT1, AKT2, AKT3, MTOR, NF-κB (RelA), PDK1, PI3K, and PTEN." (PMID 35634241, 2022). "Everolimus is an mTOR inhibitor that targets PTEN and TMEM127, and the resultant inhibitory effect is more pronounced in cancers with high METTL3 expression, albeit small molecule inhibitors of METTL3 are currently under investigation." (PMID 36561529, 2022). "Furthermore, it could be speculated that KD can increase the effect of pharmacological treatment, acting on IL-6, VEGF, and PI3K/AKT/mTOR pathways; this strengthens the idea that KD could be considered an “adjuvant cancer therapy”, translatable in the management of NETs." (PMID 36139562, 2022). "GSEA revealed that ARID1B is involved in multiple cancer-related pathways, among others PI3K-AKT and mTOR pathways, suggesting that ARID1B regulates these pathways and functions as a tumour suppressor in COAD." (PMID 36313455, 2022). "It has been found that many cancers exhibit up-regulation of the PI3K/Akt/mTOR signaling pathway, resulting in the inhibition of autophagy by mTOR protein in cancer cells and their survival." (PMID 36077839, 2022). "Cancer patients EV/PBMC media dramatically stimulated phospho-AKT and phospho-mTOR levels in A549 cells, compared to controls." (PMID 35461372, 2022). "A KEGG analysis also reflected several pathways related to cancer and immunity, including the MAPK and mTOR signaling pathways, longevity regulatory pathway, and platelet activation." (PMID 36275664, 2022). "The anti-cancer efficacy was significantly greater than single agent when neratinib, a pan-HER2 TKI, was combined with mTOR inhibition (77%) or with MEK inhibition (77%)." (PMID 36387174, 2022). "Despite the significant roles of MTOR and PROX1 in the proliferation of carcinoma cells, few studies have investigated the relationship between these two factors." (PMID 35159256, 2022). "In all the carcinoma and hematopoietic cancer networks, STAT1 and STAT3 interact with a similar panel of proteins, including MTOR, SRC and EGFR." (PMID 35229974, 2022). "RSK (ribosomal s6 kinase) is a principal effector of ERK that promotes the motility and invasive capacity of carcinoma cells, and RSK can also activate mTOR." (PMID 35884900, 2022). "Both mTOR and autophagy are upregulated in KRAS mutant cancer cells; therefore, chloroquine has been used for treating cancer in the clinic." (PMID 33925206, 2021). "Consistently, a preclinical study has reported that PI3K-AKT-mTOR pathway inhibits ferroptosis and inhibition of PI3K and mTOR can activate ferroptosis in cancer cells." (PMID 33748162, 2021). "mTOR and ERK-1/2 regulate cancer cells aggressiveness through modulating the multiple signaling pathways in human body." (PMID 33996789, 2021). "Among these commonly repressed pathways we found several routes that are frequently over-activated in cancer, such as ECM receptor interaction, focal adhesion, mTOR signaling, VEGF signaling, ERBB signaling, TGFβ signaling or WNT signaling." (PMID 34488783, 2021). "The PI3K/AKT/mTOR and the AMP-activated protein kinase pathways are more common dysregulated pathways in cancer." (PMID 33849550, 2021). "Until date, not much is known about the racially disparate expression of mTOR and ERK-1/2 pathways in cancers." (PMID 33996789, 2021). "p62 has been recognized as a new oncoprotein in various cancers including HCC, with the potential to activate multiple oncogenic signaling pathways such as mTOR and Nrf2." (PMID 33854041, 2021). "This raises the prospect that blocking MAPK6, either alone or combined with mTOR inhibitors, will be an effective therapeutic for MAPK6-high cancers." (PMID 34767444, 2021). "Autophagy, a typical cellular mechanism that represents a prospective therapeutic target in cancer treatment, is controlled by the PI3K/mTOR and AMPK signaling pathways." (PMID 34768930, 2021).
cancer (continued). "In cancer-resistant cells, the sustained activation of the AKT/mTOR is regulated by the upregulation of IGF1R, which plays a determinate role in promoting resistance to PI3K/AKT/mTOR inhibitors." (PMID 33466806, 2021). "Anti-cancer effects involve many mechanisms, including oxidative stress, intrinsic and extrinsic mechanisms, as well as the survivin, PI3K/Akt/mTOR, SHH, Nrf2/Keap1, inflammation, and autophagy pathways." (PMID 34863080, 2021). "mTOR and ERK-1/2 pathways have been the most extensively studied pathways in different cancers and their targeting has given promising results." (PMID 33996789, 2021). "Another important protein of the PI3K/AKT/mTOR pathway, PI3K, is deregulated in a wide spectrum of human cancers and the inhibition of PI3K can result in both decreased cellular proliferation and increased cellular death." (PMID 34360679, 2021). "Lactic acid production and secretion following Warburg glycolysis by cancer cells results in acidification of the TME, suppresses PI3K/Akt/mTOR pathway, and therefore inhibits T cell glycolysis." (PMID 35250965, 2021). "Among cancer signaling pathways, the phosphoinositide 3-kinase (PI3K)/protein kinase B (PKB or Akt)/mammalian target of rapamycin (mTOR) pathway promotes cellular proliferation and contributes to tumor occurrence and aggravation." (PMID 34579037, 2021). "The estrogen receptors play a significant role in cancer survival and progression through PI3K/AKT/mTOR pathway." (PMID 34122605, 2021). "Curcumin has inhibitory effects on mTOR activation and phosphorylation of p-4E-BP1 and p-70S6K1 proteins in different cancer cell lines." (PMID 34829562, 2021). "Researchers have investigated intracellular signaling pathways such as PI3K/AKT/mTOR (PAM), poly ADP-ribose polymerase (PARP), androgen receptor network, and cancer driven genes like BRCA and PIK3CA to develop new therapeutics." (PMID 33670524, 2021). "Being a chemopreventive role against different cancer cell lines, fisetin has been found to suppress the PTEN/PI3K/Akt and mTOR signaling pathway." (PMID 33473265, 2021). "For example, oncogene pathways such as mTOR, Akt, PI3KCI, Bcl-XL, Bcl-2, BCR-ABL, and Ras play an irreplaceable role in determining the survival of cancer cells." (PMID 34512368, 2021). "Such collection of bioactive compounds includes 349 experimental, investigational or FDA-approved kinase inhibitors targeting most cancer-related pathways (PI3K, HDAC, mTOR, MAPK, CDK, Aurora Kinase, JAK, etc.)." (PMID 34253243, 2021). "Inhibition of the mTOR pathway can negate the effect of HER2 hyperactivity, enhancing glycolysis in cancer cells, but prolonged inhibition of mTOR pathway activity leads to an up-regulation of ERK activation." (PMID 34208071, 2021). "EGFR is overexpressed in ~90% of HNSCC patients and drives the cancer through downstream MAPK and phosphatidylinostiol-3-kinase (PI3K)/AKT/mammalian target of rapamycin (mTOR) signaling." (PMID 33799513, 2021). "Here, we focus on current understanding of mTOR and MAPK pathways in cancer, with a particular emphasis on racially disparate regulation of these signaling pathways and their crosstalk with other key signaling molecules in different solid tumors." (PMID 33996789, 2021). "In cancer cells, SREBF1 protein is also stabilized and activated by the PI3K/Akt/mTOR signaling pathway." (PMID 34272396, 2021).
cancer (continued). "PIK3R2, a gene encoding p58β regulatory subunits that participated in most of the cancer-related and biological activity signaling pathways including PI3K, mTOR and cell cycle-apoptosis." (PMID 34299042, 2021). "Metabolic reprogramming including glucose and fatty acid metabolism, and their crosstalk, is widely observed during cancer development to support cancer cell proliferation and invasiveness, which is regulated by HIF-1 and PI3K/Akt/mTOR pathway." (PMID 34646087, 2021). "We also explored the role of hub genes in all known cancer related pathways, including Apoptosis, Cell Cycle, DNA Damage Response, EMT, Hormone AR, Hormone ER, PI3K/AKT, RAS/MAPK, RTK, and TSC/mTOR pathways." (PMID 34804966, 2021). "Differential metabolites were related with classical cancer pathways (apoptosis, cell cycle) and NET signaling (tryptophan metabolism, angiogenesis, mTOR)." (PMID 34072010, 2021). "mTOR is a crucial component of the PI3K/AKT pathway, which modulates the angiogenesis process, cell proliferation, and metabolism either in normal or in cancer cells." (PMID 34885006, 2021). "This is especially important, as mTORC2 is an essential cellular energy production element, which promotes cancer progression via lipid formation and fueling the PI3K/AKT/mTOR pathway." (PMID 34066403, 2021). "Upon assessing therapeutic responses to targeted PI3K/mTOR inhibitor BEZ235 in developed heterotypic cancer tissues, both stromal and cancer cells exhibited a decrease in pS6 following the treatment." (PMID 34577765, 2021). "Additional enriched KEGG pathways included ribosome, cell cycle, cancer-related pathways, focal adhesion, and intracellular signal transduction pathways of PI3K-Akt, MAPK, and mTOR." (PMID 35127538, 2021). "Autophagy can be induced in normal and cancer cells by multiple conditions via stimulation of specific cell sensors, where the AKT/mTOR axis represents one of the major signal transduction pathways involved." (PMID 34740374, 2021). "CRNDE was also shown to affect cancer microenvironments and metabolism via the PI3K/AKT/mTOR and Raf/MAPK pathways." (PMID 34745939, 2021). "The role of PI3K/AKT/mTOR and MAPK pathways in the regulation of translational machinery are well documented and they are frequently overactivated in most types of cancer." (PMID 33672592, 2021). "CyclinD1 plays an important role in the regulation of cancer cell cycle, which is regulated by AKT/mTOR signaling." (PMID 33834064, 2021). "mTOR inhibitors in combination with additional agents have been studied in AML and other advanced cancers." (PMID 33784031, 2021). "RTK-driven feedback reactivation of AKT or ERK signaling has been identified as a key driver of drug resistance in cancers treated with AKT and mTOR inhibitors or BRAF and MEK inhibitors." (PMID 34790119, 2021). "In PC, PI3K/AKT/mTOR and Ras/Raf/Mitogen-activated protein kinase/ERK kinase (MEK)/extracellular-signal-regulated kinase (ERK) pathways are upregulated and favor cancer cells proliferation and growth." (PMID 34579079, 2021). "GSEA showed that high LOX expression is related to ECM receptor interaction, cancer, Hedgehog, TGF-beta, JAK-STAT, MAPK, Wnt, and mTOR signaling pathways." (PMID 34595188, 2021). "We checked mTOR expression in wt and yotari livers since reelin activates PI3K/Akt/mTOR, a pathway that is often hyperactivated in cancers." (PMID 34639052, 2021). "The interesting point is that anti-tumor compounds including cryptotanshinone suppress cancer proliferation and induce apoptosis via PTEN upregulation and the subsequent inhibition of PI3K/Akt/mTOR and nuclear factor-kappaB (NF-ĸB) pathways." (PMID 33670518, 2021). "Manassantin and arctigenin are plant lignans with anti-cancer activities, and regulates multiple important signaling pathways, including NF-kappa B, PI3K/Akt/mTOR, and MAPK/ERK, Notch-1, and p38." (PMID 34490085, 2021). "mTOR signaling pathway is indeed frequently activated in RCC, inducing cancer cell proliferation and survival." (PMID 33791295, 2021).
cancer (continued). "The compounds contained in propolis inhibit multiple signaling pathways crucial for cancer initiation, progression, and metastasis, such as PI3k/AKT/mTOR, NFκB, JAK-STAT, TLR4, VEGF, TGFβ, and intrinsic and extrinsic apoptosis pathways." (PMID 34444754, 2021). "Increasing studies have been focused on the development of small-molecule inhibitors targeting components of PI3K/Akt/mTOR and RAS-RAF-MEK-ERK signaling as cancer therapeutics." (PMID 34326318, 2021). "The interplay between mTOR and ERK-1/2 signaling pathways is a key determinant of cancer progression and metastasis." (PMID 33996789, 2021). "On the one hand, the anti-cancer property of metformin is mainly attributed to the activation of AMP-activated protein kinase (AMPK) and inhibition of the mammalian target of rapamycin (mTOR)." (PMID 33809969, 2021). "As a master regulator of cancer, the PI3K/Akt/mTOR signaling pathway has been demonstrated previously to be involved in regulatory T cell/T helper 17 cell (Treg/Th17) differentiation." (PMID 33499090, 2021). "In particular, HIF-1α has been found to promote the stemness of cancer cells through the regulation of several pathways, including PI3K/Akt/mTOR, Wnt/β‐catenin, and Notch signaling." (PMID 33461544, 2021). "Latcripin-1 treatment also suppressed Akt/mTOR phosphorylation and PI3K expression, which are critically involved in cancer progression." (PMID 34444724, 2021). "In malignant tumors, the PI3K/AKT/mTOR pathway plays a critical role in the malignant transformation of human tumors and their subsequent growth, proliferation, and metastasis." (PMID 33819917, 2021). "Reciprocally, inhibition of the PI3K/AKT/mTOR pathway has shown to control CD4+ regulatory T-cells activity and enhance cancer cell recognition by the immune system in vivo." (PMID 33546207, 2021). "Studies have reported that activation of the mTOR, cAMP and MAPK signaling pathways plays an important role in the proliferation and migration of cancer." (PMID 34799549, 2021). "It is worth highlighting the presence of predictive biomarkers for drugs that are currently in use for treating different cancers, such as PARP, ERBB2, EGFR, PIK3CA, mTOR, and Hedgehog signaling inhibitors." (PMID 34575676, 2021). "When we correlated the expression levels of mTOR and LARP1 in a series of cancer cases, there was a weakly positive correlation between the two (r = 0.29) indicating LARP1 and mTOR often function independently of each other." (PMID 32233986, 2021). "Akt can also promote IKK activity indirectly through mTOR and the mitogen-activated protein kinase (MAP3K) cancer osaka thyroid (Cot)." (PMID 34829868, 2021). "Significant alterations in p38 and PI3K/Akt/mTOR after AR, AA, AB, and AB23A treatments in various cancer cells were observed." (PMID 34371964, 2021). "Differential metabolites identified were related with classical cancer pathways (apoptosis, cell cycle) and NET signaling (tryptophan metabolism, angiogenesis or the mTOR pathway)." (PMID 34072010, 2021). "In GBM, we found that the high expressions of 25 genes activate or inhibit eight cancer-related pathways, namely, TSC/mTOR, hormone AR, hormone ER, DNA damage response, RTK, EMT, apoptosis, and cell cycle (FDR < 0.05)." (PMID 34589481, 2021). "The CTD2 data set had a total of 79 unique drugs with sensitivities across 351 cancer cell lines that involve 22 targets, such as EGFR, HDAC1, MTOR, MET, ERBB2, and BRAF." (PMID 33795761, 2021). "DPPIV plays a significant role in cancer biology and inhibition of DPPIV promotes cancer metastasis via induction of the CXCL12/CXCR4/mTOR/EMT axis, implying a dissemination-suppressive role in cancer." (PMID 34228231, 2021).